HSD11B1 (hydroxysteroid 11-beta dehydrogenase 1)
Diseases named in the same sentence as HSD11B1 in open-access papers (continued):
Sharing a sentence is not in itself a finding about the gene and the disease.
metabolic syndrome (23 papers, 2011 to 2025). A cluster of metabolic risk factors for CARDIOVASCULAR DISEASES and TYPE 2 DIABETES MELLITUS. "Other authors studying this issue showed that the presence of the G rs846910 allele of the HSD11B1 gene is accompanied by a higher risk of developing diabetes and metabolic syndrome." (PMID 34639470, 2021). "As reported in the literature, genetic variants in the HSD11B1 gene are promising contributors to type 2 diabetes (T2D) and metabolic syndrome (MetS)." (PMID 34639470, 2021). "Rodent genetic studies have suggested that increased Hsd11b1 expression or activity increases the risk of several components of metabolic syndrome." (PMID 34209784, 2021). "Other authors have also studied the association between the presence of metabolic syndrome or type 2 diabetes and polymorphisms of the HSD11B1 gene, especially the rs846910 polymorphism." (PMID 34639470, 2021). "The HSD11B1 gene encodes the type 1 isoform of 11-β-hydroxysteroid dehydrogenase, which converts glucocorticoids into the active form, which plays an important role in the regulation of metabolic syndrome and immune response." (PMID 34845968, 2021). "Since The HSD11B1 gene encodes the type 1 isoform of 11-β-hydroxysteroid dehydrogenase, which converts glucocorticoids into the active form, which plays an important role in the regulation of metabolic syndrome and immune response." (PMID 34845968, 2021). "Indeed 11-Dehydrocorticosterone causes metabolic syndrome, which is prevented when HSD11B1 is knocked out in livers of male mice." (PMID 33318609, 2020). "Moreover, polymorphisms in HSD11B1 have been linked to insulin resistance and metabolic syndrome in multiple populations." (PMID 22808055, 2012). "During the elevation of reverse cortisone oxo-reductase activity of HSD11B1, the excessive and chronically sustained cortisol might promote adipocyte differentiation and inhibit pre-adipocyte proliferation, hence causing metabolic syndrome and dyslipidemia." (PMID 30388854, 2018). "And Hsd11b1 (11β-HSD1) gene deficiency shields mice against glucose intolerance, dyslipidemia, and obesity." (PMID 38993560, 2024). "The 2-week Ca-deficient diet in rats was associated with the upregulation of the hepatic expression of Hsd11b1 mRNA, which occurred before the animals developed obesity or overt features of metabolic syndrome." (PMID 34209784, 2021). "Recently, HSD11B1 has been investigated as a novel target of potential therapeutic drugs for metabolic syndrome, including Cushing syndrome." (PMID 29206210, 2017). "In our study, HSD11B1-TG male pigs were generated as a disease model for metabolic syndrome by somatic cell nuclear transfer (SCNT) using recloned fibroblasts." (PMID 29206210, 2017). "Consistent with our findings, another study demonstrated that steroidogenesis-related HSD11B1 deficiency prevents the development of metabolic syndrome, however, the study’s mechanism was not made explicit." (PMID 41385510, 2025). "Conversely, overexpression of HSD11B1 (corticosteroid 11-beta-dehydrogenase isozyme 1), which catalyzes the conversion of the active form of cortisol, has been found to result in visceral obesity, insulin-resistant diabetes, and dyslipidemia." (PMID 38246999, 2024). "Diminished HSD11B1 activity has been previously reported in PCOS and may result in a shift of steroidogenesis towards the more active glucocorticoid products associated with hypercortisolemic adverse effects often manifesting as the metabolic syndrome." (PMID 30308019, 2018). "The Dex-treated rats’ heart proteomes showed an increase in the levels of the enzyme hydroxysteroid 11-beta dehydrogenase 1(HSD11B1), which is known to augment GC action and increase the adverse effects of the drug, leading to increased insulin resistance, dyslipidemia, and hypertension." (PMID 31247941, 2019).
Insulin resistance (17 papers, 2012 to 2026). Increased resistance towards insulin, that is, diminished effectiveness of insulin in reducing blood glucose levels. "Hsd11b1 has been reported to be associated with glucocorticoid-induced insulin resistance and the mediation of insulin release in pancreatic islets." (PMID 35741777, 2022). "Given the high prevalence of insulin resistance in subjects, studies will be needed to evaluate the effects of these blockers in subjects with different HSD11B1 gene variants." (PMID 34639470, 2021). "In our study we also showed an association between the presence of rs846910 polymorphism of the HSD11B1 gene and the risk of insulin resistance." (PMID 34639470, 2021). "For instance, increased HSD11B1 activity in skeletal muscle is linked with the development of insulin resistance, a decrease of muscle mass, and elevated gene expression associated with muscle atrophy." (PMID 32316389, 2020). "Overexpression or dysregulation of HSD11B1 has been associated with metabolic disorders eliciting abdominal obesity, hyperglycemia, hyperphagia, hyperleptinemia, and insulin resistance." (PMID 29206210, 2017). "The results of our study suggest that the determination of rs846910 or rs12086634 polymorphism of the HSD11B1 gene may in the future find practical application in subjects with suspected insulin resistance." (PMID 34639470, 2021). "Thus, we hypothesized that a higher degree of insulin resistance would be associated with increased hepatic HSD11B1 activity." (PMID 32069218, 2020). "Though this would normally indicate insulin resistance and high glucose levels, corresponding AUC glucose values show lower glucose concentration in Hsd11b1-/- mice compared to WT mice when challenged with the same amount of glucose (3g/kg)." (PMID 36246869, 2022). "Maternal Ca restriction during pregnancy alters postnatal growth, Hsd11b1 expression, and insulin resistance in a sex-specific manner." (PMID 34209784, 2021). "Our results provide a basis to begin basic research on the role of the HSD11B1 gene in the pathogenesis of insulin resistance." (PMID 34639470, 2021). "Hsd11b1-transgenic (TG) mice show abdominal obesity, hyperglycemia, insulin resistance, hyperphagia, hyperleptinemia and increased intra-adipose and portal levels, but not systemic corticosterone levels." (PMID 29206210, 2017). "Overexpression of the HSD11B1 gene in adipocytes has been shown to be related to high cortisol concentrations in adipose tissue and to the development of central obesity, insulin resistance (IR), and diabetes in mouse models." (PMID 26056536, 2015). "This study was designed to assess the association between four polymorphic sides in HSD11B1 (rs12086634, rs846910, rs4844880, rs3753519) between subjects with and without insulin resistance in the Polish population of people living in Upper Silesia." (PMID 34639470, 2021). "Overexpression of Hsd11b1 in either liver or adipose tissue renders mice insulin resistant, conversely knockout of this gene protects mice from glucocorticoid-induced insulin resistance." (PMID 28443133, 2017). "Mice that overexpress Hsd11b1 in adipose tissue develop visceral obesity and insulin resistance." (PMID 24427280, 2014).
diabetes (9 papers, 2014 to 2025). "We observed significantly lower expression levels of each gene in visceral tissues of diabetic patients than in obese subjects without diabetes: p < 0.001 for GR, p < 0.0001 for H6PDH, p < 0.01 for HSD11B1, and p < 0.0001 for HSD11B2." (PMID 38791098, 2024).
Hypertension (9 papers, 2008 to 2025). The presence of chronic increased pressure in the systemic arterial system. "HSD11B1 overexpression in mice has been associated with dose-dependent hypertension and AGT expression in liver." (PMID 24658007, 2014). "Polymorphisms in HSD11B1 have been associated with type 2 diabetes and hypertension." (PMID 18611262, 2008). "Several genes, including CYP17A1, CYP11B2, HSD11B1, CYP11B1, and NR3C2, which are implicated in the control of hypertension, regulate the synthesis of steroid hormones, such as glucocorticoids, mineralocorticoids, androgens, and estrogens." (PMID 37571339, 2023).
breast carcinoma (8 papers, 2008 to 2024). "Two out of five tagging SNPs in HSD11B1 were associated with breast cancer (rs11807619, P = 0.006; rs932335, P = 0.0001)." (PMID 18611262, 2008). "The Renca cell line, which expressed the highest levels of Hsd11b1 and Hsd11b2 compared to mouse melanoma, breast cancer, colon cancer and hepatoma cell lines, was selected as a syngeneic renal cancer model for in vivo studies." (PMID 38170044, 2024). "For instance, glucocorticoid signaling opposes the development of estrogen-dependent breast cancers, and breast cancers downregulate the expression of HSD11B1 reducing glucocorticoid availability within the tumor." (PMID 37143725, 2023). "Our results suggest that common variation in HSD11B1 and IRS2 may be associated with breast cancer among postmenopausal women." (PMID 18611262, 2008). "Although these data suggest that HSD11B1 and IRS2 may be associated with risk for breast cancer, it is also possible that these findings are due to chance." (PMID 18611262, 2008). "Our results suggest that common variation in HSD11B1 and IRS2 may be associated with breast cancer among postmenopausal white women." (PMID 18611262, 2008). "However, 11 SNPs in HSD11B1 were included in a recent genome-wide scan of breast cancer and none were associated with breast cancer, including SNPs that were highly correlated with ours." (PMID 18611262, 2008). "In women with breast cancer, abundance of CYP19A1 transcript was positively correlated with HSD11B1 mRNA expression (r = 0.54; P = .0326)." (PMID 31853538, 2020). "We also observed suggestive association for UGT2B11 in breast and endometrial cancer as well as for HSD11B1, SULT2A1 and SULT2B1 in breast cancer." (PMID 20617168, 2010). "Our findings suggest that these tagging SNPs in HSD11B1 and IRS2 mark regions of the genome that may harbor risk alleles for breast cancer, and these associations are probably independent of adiposity." (PMID 18611262, 2008).
type 2 diabetes (8 papers, 2008 to 2022). "Recently, metformin was shown to increase hepatic HSD11B1 activity in subjects with type 2 diabetes, an effect likely linked to increased insulin sensitivity." (PMID 32069218, 2020). "In a study using db/db mice, it has been reported that increased expression of GR and HSD11B1 in hepatocytes is an important component in the development of type 2 diabetes." (PMID 29206210, 2017). "Among obese individuals without type 2 diabetes diet-induced weight loss has been associated with decreased excretion of GC metabolites in urine, decreased expression of HSD11B1 in adipose tissue but unaltered hepatic HSD11B1 activity." (PMID 32069218, 2020). "This is important since HSD11B1 has been highlighted as a potential drug target in type 2 diabetes." (PMID 32069218, 2020). "HSD11B1 might be related to BMD and is associated with the onset of type 2 diabetes." (PMID 35328013, 2022). "However, among obese individuals with type 2 diabetes, hepatic HSD11B1 activity is sustained." (PMID 32069218, 2020). "Previous studies have suggested that a relative insulin deficiency in type 2 diabetes may be the cause of sustained hepatic HSD11B1 activity compared to obese individuals without type 2 diabetes." (PMID 32069218, 2020). "Previously, we have shown that a 2-year intervention with a PD associated with a 5–10% weight reduction increased the systemic activity of 5α-reductase and reduced the expression of HSD11B1 in s.c. adipose tissue among obese women without type 2 diabetes." (PMID 32069218, 2020). "Therefore, HSD11B1 and H6PD polymorphisms analyzed individually may not be associated with type 2 diabetes and MetS." (PMID 31558916, 2019).
osteoporosis (5 papers, 2012 to 2025). A condition of reduced bone mass, with decreased cortical thickness and a decrease in the number and size of the trabeculae of cancellous bone (but normal chemical composition), resulting in increased fracture incidence. "Excessive Hsd11b1 activation elevates local glucocorticoid activity in adipose and bone tissues, thereby promoting visceral fat accumulation, impaired insulin sensitivity, and osteoporosis associated with aging." (PMID 41019552, 2025). "Taken together, the here generated HSD11B1 loss-of-function and gain-of-function cell models provide a novel and powerful tool for analyzing the role of 11β-HSD1 in the onset of age-related osteoporosis and could help to identify new therapeutic strategies." (PMID 36091434, 2022). "Notably, HSD11B1 expression in osteoblasts and suppressed cortisol levels in patients evaluated for osteoporosis increase with age." (PMID 36091434, 2022).
central obesity (4 papers, 2013 to 2023). "It is true that over-expression of 11β-HSD1 gene (Hsd11b1) in the fat tissue of mice caused central obesity, disturbed lipid profiles and insulin resistance." (PMID 23533564, 2013). "The increased corticosterone, in turn, triggered adipose local Hsd11b1 expression, thereby leading to central obesity in estrogen-depleted females." (PMID 37834368, 2023). "The summary data have shown that HSD11B1 expression in abdominal SAT and VAT is related with central obesity and body size." (PMID 26056536, 2015). "In four studies HSD11B1 expression in abdominal SAT was positively related with measures of body size and central obesity, namely respectively, BMI and intra-abdominal VAT volume estimated by MRI." (PMID 26056536, 2015).
depression (4 papers, 2012 to 2025). "Since polymorphisms in the HSD11B1 gene have been associated with increased risk for Alzheimer's disease and susceptibility to incident depression, HSD11B1 inhibitors should specifically be tested for their effects in patients affected by Alzheimer's disease or depression." (PMID 22809392, 2012). "During pregnancy, the greatest self-depression scores were found in women with the GG genotype in the rs1256540 position of HSD11B1 gene." (PMID 35203999, 2022). "Changes in SNP in HSD11B1 and SERPINA6 genes turned out to be statistically important in self-reported self-esteem results and depression prevalence." (PMID 35203999, 2022).
melanoma (4 papers, 2023 to 2025). A malignant, usually aggressive tumor composed of atypical, neoplastic melanocytes. "Importantly, high levels of HSD11B1 expression in melanoma have been linked to poor responses to immune checkpoint inhibitors." (PMID 40917881, 2025). "In melanoma, HSD11B1 is an enzyme that can convert inert glucocorticoid into active glucocorticoid, and mice with high expression of HSD11B1 exhibit attenuated infiltration of CD4+ T cells and CD8+ T cells and are insensitive to PD-1 inhibitors." (PMID 39403382, 2024). "Altered expression of HSD11B1 is also apparent in around 5% of studies on endometrial cancers, non-Hodgkin lymphomas, non-small cell lung cancers and melanomas." (PMID 36940215, 2023). "HSD11B1, an enzyme crucial for regulating glucocorticoid activity in tissues, exhibits expression in various cellular compartments, including myeloid cells, T cells, and melanoma cells." (PMID 40917881, 2025). "In addition, our findings are consistent with a recent study demonstrating that HSD11B1 limits the response to PD-1 blockade in melanoma." (PMID 38170044, 2024).
atherosclerosis (3 papers, 2022 to 2025). A disease characterized by the build-up of fatty material and calcium deposition in the arterial wall resulting in partial or complete occlusion of the arterial lumen. "HSD11B1 regulates cortisol production from cortisone, and its upregulation has been associated with stress, chronic inflammatory conditions like atherosclerosis, inflammatory bowel disease, and colitis." (PMID 40589518, 2025). "In addition, cluster 0 expressed Serpinf1, involved in ossification and osteoblast differentiation, Hsd11b1, shown to exacerbate atherosclerosis, Pex5l, expressed in macrophages and Gfra2 in monocytes, as well as cystatin C, associated with coronary artery calcification." (PMID 35163719, 2022).
colitis (3 papers, 2019 to 2025). Inflammation of the colon. "Therefore, the increased levels of PBLD, FAM3D, KRT8, SULT2B1, GPA33, DEPTOR, and decreased expression of ACSL4, IFITM1 and HSD11B1 caused by mEVs has been demonstrated to attenuate colitis, implying that consumption of mEVs has the potential to improve intestinal health." (PMID 35893911, 2022). "HSD11B1 exerts an important role in the inflammatory response, and the high expression of HSD11B1 will increase the incidence of colitis." (PMID 35893911, 2022). "However, in a murine model of acute colitis we observed the opposite, where we found a significant upregulation of Hsd11b1 and a downregulation of Hsd11b2 upon colitis induction." (PMID 31316505, 2019).
Hyperglycemia (3 papers, 2015 to 2019). An increased concentration of glucose in the blood. "Thus, HSD11B1-TG hepatocytes will be useful for studying metabolic diseases such as hyperglycemia and fatty liver disease." (PMID 29206210, 2017).
polycystic ovary syndrome (3 papers, 2008 to 2015). A disorder that manifests as multiple cysts on the ovaries. "Polymorphisms in HSD11B1 have been investigated associated with metabolic phenotype in human, including hyperandrogenemia, type 2 diabetes and hypertension." (PMID 26452272, 2015). "HSD11B1 variation has also been associated with polycystic ovarian syndrome, and ovarian steroids have been shown to regulate 11β-hydroxysteroid dehydrogenase expression in experimental models." (PMID 18611262, 2008).
sarcopenia (3 papers, 2022 to 2025). Progressive decline in muscle mass due to aging which results in decreased functional capacity of muscles. "Our study aimed to investigate glucocorticoid metabolism, including the expression of HSD11B1 in skeletal muscle, in patients with sarcopenia." (PMID 37943405, 2023). "The findings demonstrated that FOXO1, CTH, HSD11B1, GSTK1, and SPTSSA were the five sarcopenia model genes (SMGs) that were included in the LASSO regression model." (PMID 41325398, 2025). "LASSO regression identified CTH and IDI1 for IPF, and FOXO1, CTH, HSD11B1, GSTK1, and SPTSSA for sarcopenia." (PMID 41325398, 2025).
steatosis (3 papers, 2020 to 2024). Increased lipid within the cytoplasm of cells. "It has been suggested that steatosis is associated with decreased conversion of cortisone to cortisol by hepatic HSD11B1, whereas steatohepatitis might lead to increased conversion." (PMID 32069218, 2020). "Liver-specific overexpression of HSD11B1 in HFD-fed mice down-regulates LXRα and tends to ameliorate steatosis." (PMID 35614477, 2022).
Anxiety (2 papers, 2019 to 2022). Intense feelings of nervousness, tension, or panic often arise in response to interpersonal stresses. "Finally, we assessed the moderating influence of candidate genes whose level of methylation is associated with the Nr3c1 genotype on anxiety-like behavior: Ank3, Avp, Avpr1a, Avpr1b, Bdnf, Cacna1c, Cyp11b1, Cyp11b2, Fkbp5, Hsd11b1, Igf2, Morc1, Nr3c1, Oxt, Oxtr, Pclo, Slc6a4." (PMID 30655507, 2019).
asthma (2 papers, 2015 to 2023). "Based on previous studies and the uncontentious efficacy of corticosteroid therapy in asthma patients, we here investigated the role of 11β-hydroxysteroid dehydrogenase 1 (11β-HSD1/Hsd11b1)-dependent local GC reactivation in the regulation of allergic airway inflammation." (PMID 37936704, 2023).
colon cancer (2 papers, 2021 to 2024). "Previous studies have shown that glucocorticoids encoded by HSD11B1 contribute to the regulation of cell proliferation and differentiation, and recognized the important role HSD11B1 play in promoting the development and progression of colon tumors and adenocarcinoma cells." (PMID 34845968, 2021).
colorectal cancer (2 papers, 2018 to 2023). A primary or metastatic malignant neoplasm that affects the colon or rectum. "Compared with HSD11B2 isoform, the role of HSD11B1 in tumor biology remains elusive although an increased HSD11B1 mRNA expression was reported in adrenal cortical neoplasms and colorectal cancers." (PMID 30388854, 2018).